ENSG00000252050
Gene: Small nucleolar RNA gene on chromosome X (38,308,112 to 38,308,241, reverse strand). Ensembl gene ENSG00000252050.
Homologues: Paralogues in human: SNORA31B (81% identical), SNORA31 (66% identical).